ATM (ATM serine/threonine kinase)
Diseases named in the same sentence as ATM in open-access papers (continued):
Sharing a sentence is not in itself a finding about the gene and the disease.
cervical carcinoma (continued). "In addition to this, we provide additional evidence concerning the beginning of the DDR pathway in CSC from cervical cancer, where ATM, H2A.X, and PARP1 are key elements involved in the detection of DNA damage." (PMID 31073313, 2019). "Furthermore, cervical cancer cells treated with isoliquiritigenin (ISL) displayed an activated ATM that activated its downstream effectors." (PMID 23773282, 2013). "However there is a conflicting report that suggested that ATM mediated signaling induced cell cycle arrest in cervical cancer cells." (PMID 23773282, 2013). "To investigate whether indeed ATM activity has predictive value for response to (chemo)radiation, we examined phospho-Ser1981-ATM [phosphorylated ATM (p-ATM)] levels in pre-treatment cervical cancer tissues." (PMID 22323184, 2012). "Finally, we tested the predictive and prognostic properties of ATM pathway activity in tumours in a large, well-documented and consecutive series of patients with cervical cancer primarily treated with (chemo)radiation." (PMID 22323184, 2012). "DNA repair pathway genes, such as BRCA1, BRCA2 and ATM, which are potential predictive biomarkers, also had a high frequency of CNVs in the present study, suggesting that HR defect might serve as a therapeutic target in cervical cancer." (PMID 35205332, 2022). "In addition to being related to cervical cancer, ATM is also related to other malignant tumours." (PMID 35379200, 2022). "We hypothesize that SKP2 may interact with MRN associated protein complex and trigger ubiquitination of these associated proteins upon DSBs, which is critical for facilitating ATM recruitment for DNA damage repair and improve radioresistance of cervical cancer cells." (PMID 27317767, 2016). "However, we found that high p-ATM expression was related to worse disease-specific survival (HR = 1.418; p = 0.038) in univariate analysis, again underscoring a role for ATM activity in cervical cancer behaviour." (PMID 22323184, 2012). "In addition, targeting ATM kinase activity could be an interesting therapeutic option to sensitise tumour cells for (chemo)radiation in patients with cervical cancer who have high tumour levels of active ATM before start of (chemo)radiotherapy." (PMID 22323184, 2012). "The transcription factor KLF13 (Krüppel-like factor 13) is vital for ATM activity and for STAT5 activation, and some studies showed that pSTAT5 plays a major role in cervical cancer pathogenesis." (PMID 38999946, 2024). "We show that the down-regulation of ATM, BRCA1, and CHEK2 genes expression selectively affected HPV-positive cervical cancer-derived cells proliferation/viability." (PMID 35745491, 2022). "Other reports have also indicated that ATM, PCNA, and HMGB1 are highly expressed in cervical cancer tissues, and ABCG2 is expressed at low levels in cervical cancer tissues." (PMID 35379200, 2022). "Silencing or chemical inhibition of ATM/CHK2 reduced the clonogenic and proliferative capacity of cervical cancer-derived cells." (PMID 35745491, 2022). "Given its significance in regulating autophagy and apoptosis, targeting the BMI1/ATM/miR-16 circuit may hold therapeutic potential in treating NSCLC and cervical cancer by modulating cell survival and death responses." (PMID 37767112, 2023). "Our results show that, upon ATM inhibition with caffeine or KU-55933, proliferation is strongly impaired in both cervical cancer cell lines, but not in PHK." (PMID 35745491, 2022).
cervical carcinoma (continued). "We identified that inhibition of the ATM/CHK2/BRCA1 axis selectively affects the proliferation of cervical cancer-derived cell lines, without altering normal primary human keratinocytes (PHK) growth." (PMID 35745491, 2022). "Among them, PLK1, ATM, CDK5 and CHEK1 are abnormally expressed in cervical cancer." (PMID 32655987, 2020). "In addition, our study also suggested the possibility of combining targeted agents such as ATM inhibitors and HDAB to induce a synergistic lethal response for the treatment of cervical cancer." (PMID 26041102, 2015). "In this study, low concentrations of HDAB initiates the cell programmed death of cervical cancer cells, indicating that HDAB might result in persistent double strand breaks and therefore ATM elicits a strong apoptotic signal." (PMID 26041102, 2015). "Our data showed that HDAB elicited DNA damage and activated the ATM-dependent DNA repair pathway, but not the DNA-PK pathway, in cervical cancer cells." (PMID 26041102, 2015). "To test the specificity of antibodies in paraffin-embedded material, we analysed paraffin-embedded cervical cancer cell lines irradiated in the presence or absence of ATM inhibitors." (PMID 22323184, 2012). "Concordantly, clonogenic survival analysis revealed that ATM inhibition, but not 53BP1 depletion, strongly radiosensitised cervical cancer cells." (PMID 22323184, 2012). "Consistent with this hypothesis, the inhibition of ATM activation by the ATM-specific inhibitor CGK733, but not the DNA-PK-specific inhibitor NU7026, effectively abolished the HDAB-induced S phase arrest and enhanced apoptosis and colony formation inhibition in cervical cancer cells." (PMID 26041102, 2015).
Lynch syndrome (38 papers, 2016 to 2025). An autosomal dominant hereditary neoplastic syndrome characterized by the development of colorectal carcinoma and a high risk of developing endometrial carcinoma, gastric carcinoma, ovarian carcinoma, renal pelvis carcinoma, and small intestinal carcinoma. "Other genes, such as CHEK2, ATM, and PALB2 and Lynch syndrome genes, are also implicated in ovarian cancer." (PMID 32127576, 2020). "Similarly to studies on Western populations, mutations in genes other than those associated with the Lynch syndrome, including MUTYH, BRCA2, ATM, BRIP1, CDKN2A, and NF1, were identified." (PMID 39061183, 2024). "Germline variants in the ATM gene were found more consistently across multiple primary tumor types and demonstrated a more consistent fraction of the overall germline variant burden than hereditary breast cancer (BRCA1/2) or Lynch syndrome genes in different tumors." (PMID 36261688, 2023). "For patients without Lynch syndrome, APC was identified as the gene associated with the most mutations (n = 14) and was followed by BRCA1 (n = 8), RAD50 (n = 7), MUTYH (n = 5), ATM (n = 5), and BRCA2 (n = 4)." (PMID 35014770, 2022). "PVs in BRCA1, but not BRCA2, PALB2, ATM, CHEK2, or Lynch syndrome genes, were associated with elevated RS on multivariable analysis (P < .001)." (PMID 33426465, 2021). "In our study, 8 patients were identified with pathogenic or likely pathogenic germline mutations in non-Lynch syndrome genes (MUTYH, GALNT 12, POLE, MPL, ATM, and ERCC4), which indicated that there may be other genes outside of Lynch syndrome associated with endometrial cancer." (PMID 30886832, 2019). "In addition, we identified 2 patients who had a deleterious germline mutation in Lynch syndrome genes (MLH1 and MLH2), and another 8 patients harbored germline mutations of 6 non-Lynch syndrome genes (MUTYH, GALNT12, POLE, MPL, ATM, and ERCC4) which may be associated with endometrial cancer." (PMID 30886832, 2019).
endometrial cancer (32 papers, 2015 to 2025). Primary or metastatic malignant neoplasm involving the endometrium (mucous membrane that lines the endometrial cavity). "A TCGA pan-cancer study reported that ATM somatic mutations were most frequent in endometrial cancer." (PMID 37109350, 2023). "The pathogenic mutation in ATM gene identified in this study (c.2502_2503insA) was found in a patient with family history positive for PanC and endometrial cancer, who presented also the BRCA2 pathogenic variant c.8954_8955delTTinsAA." (PMID 36717774, 2023). "On follow up, the first patient with ATM variant (rs531617441) developed stage 1 endometrial cancer after four years." (PMID 37277882, 2023). "Biologically, the coexistence of MSI-H and deleterious DNA damage response (DDR) pathway mutations (BRCA2 and ATM) may drive a hypermutated phenotype, as reported in subsets of colorectal and endometrial cancers." (PMID 41149460, 2025). "The ATM-Chk2 pathway frequently has mutations or decreased expression, not only in hereditary cases, but also in many types of cancers, such as endometrial cancer, breast cancer, pancreas cancer, head and neck squamous cell cancer, and non-small-cell lung cancer." (PMID 31805725, 2019). "ATM mutations or functional defects may be prognostic markers for endometrial cancer." (PMID 37109350, 2023). "The ATM signaling pathway, because of its central role in cell division and DNA repair, has been a focus of cancer research, especially endometrial cancer, for exploring novel molecular therapies targeting ATM pathways." (PMID 32575462, 2020). "In this study, we investigated the anti-tumor effect of inhibitors of the ATR-Chk1 and ATM-Chk2 pathways in endometrial cancer cells." (PMID 31805725, 2019). "Recently, in two progesterone responsive and progesterone-insensitive human endometrial cancer cell lines, ATM protein was shown by reverse-phase protein array (RPPA) to participate in progesterone stimulation to suppress carcinogenesis in the endometrium." (PMID 31157162, 2019). "The significance of ATM in cancer progression and patient prognosis has been shown in studies on tissue samples from gastric, pancreatic, bladder and endometrial cancers." (PMID 26275218, 2015). "Jaceosidin inactivates Cdc25C-Cdk1 through ATM-Chk1/Chk2 activation, resulting in cell cycle G2/M arrest in endometrial cancer cells." (PMID 26147394, 2015). "ATM inhibitors have good antitumor activity and clinical application potential of radio-/chemo-sensitization, and they also exhibit preliminary activity in endometrial cancer, which needs to be further verified in clinical research." (PMID 37109350, 2023). "Thus, a functional decline of ATM and ATR was associated with the process of the carcinogenesis or malignancy of endometrial cancer." (PMID 31805725, 2019). "STK11 and ATM appeared as risk modifiers in our screen and are frequently mutated somatically but not in endometrial cancer (COSMIC database)." (PMID 26517685, 2015). "Interestingly, tissue microarray analysis of samples from endometrial cancer patients showed a correlation between ATM positivity, disease progression and increased probability of recurrence, pointing towards the oncogenic nature of ATM." (PMID 26275218, 2015). "In this study, we examined the anti-tumor effect of the inhibitors of the ATR-Chk1 or ATM-Chk2 pathway in endometrial cancer cells treated with DXR or CDDP, used as standard chemotherapeutic drugs in endometrial cancer treatment." (PMID 31805725, 2019).
endometrial cancer (continued). "In this study, we investigated the anti-tumor effect of inhibitors of these pathways in vitro by assessing the effect of the combination of ATM or ATR inhibitors and conventional DNA-damaging therapy (doxorubicin (DXR), cisplatin (CDDP), and irradiation) on endometrial cancer cells." (PMID 31805725, 2019). "Additionally, a progressive loss of ATM levels from hyperplasia to the lowest levels was observed in type 1 endometrial cancer lesions and there was a negative relationship of the pathological grades and ATM levels." (PMID 31157162, 2019). "Therefore, in this study, we aimed to clarify the anti-tumor effect of an ATR inhibitor or an ATM inhibitor combined with DXR, CDDP, or irradiation, and if the combination of the ATR inhibitor and the Chk1 inhibitor could induce DNA damage in endometrial cancer cells." (PMID 31805725, 2019). "Lower HRD rates in endometrial cancers (10–15%) and assay insensitivity to non-BRCA genes (e.g., ATM, CDK12) demand cancer-specific validation." (PMID 40864792, 2025). "As for the effect of the ATR inhibitor or the ATM inhibitor in endometrial cancer, a previous report showed that the ATR inhibitor ETP46464 enhanced the effect of CDDP in endometrial cancer cells, but the ATM inhibitor KU55933 did not." (PMID 31805725, 2019). "Regarding the effect of ATR inhibitors and ATM inhibitors in endometrial cancer, the ATR inhibitor ETP46464 enhances the anti-tumor effect of CDDP in endometrial cancer cells, but the ATM inhibitor KU55933 does not, while both the inhibitors enhance the effect of irradiation." (PMID 31805725, 2019).
diabetes (29 papers, 2006 to 2026). "There have been no reported distinct cutaneous findings noted in heterozygous ATM gene carriers; however, an association with diabetes and cancer (breast, in particular) has been noted." (PMID 40995169, 2025). "One study observed that TT genotype of the ATM rs189037 polymorphism was associated with lower prevalence of diabetes mellitus in the general population." (PMID 28806901, 2017). "When ATM gene is mutated, this event appears to contribute to the development of insulin resistance and type 2 diabetes mellitus (T2DM)." (PMID 28806901, 2017). "The genotypes of ATM rs189037 polymorphism were tested for interactions with major risk factors of diabetes mellitus, such as CAD, hypertension, smoking, UA and lipid profiles." (PMID 28806901, 2017). "As ATM deficiency is already associated with defective glucose homeostasis and mild diabetes, we predicted that blood glucose concentrations would also be reduced in A-T." (PMID 27538496, 2016). "Variant ATM heterozygotes have an increased risk of developing cancer, cardiovascular diseases, and diabetes." (PMID 27599564, 2016). "The basis for the surprising observation that polymorphisms in the ATM locus influence efficacy of metformin in diabetes treatment remains obscure." (PMID 23185347, 2012). "ATM deficiency always accompanies insulin resistance and diabetes or its complicating diseases." (PMID 38385859, 2024). "Notably, patients with ATM loss of function mutations have a higher incidence of (obesity-independent) diabetes." (PMID 32810137, 2020). "The aim of this study was to evaluate if the genetic variants in SLC22A1 rs622342 and ATM rs11212617 could be effective predictors of islet function improvement in patients with type 2 diabetes mellitus (T2DM) on metformin treatment." (PMID 32454819, 2020). "Dysfunction of ATM is known to result in diabetes by increasing ROSs followed by abnormal activation of the ASK1/JNK pathway." (PMID 30057676, 2018). "These relationships have led to the proposal that cytoplasmic ATM is a potential therapeutic target for diabetes, cancer, and neuronal degeneration." (PMID 26465009, 2015). "Drug response related SNP assessment revealed that the SAIF genome carried a SNP in the ATM gene that predicts a favorable response to metformin used in treating diabetes." (PMID 22938532, 2012). "As India has a high burden of diabetes, we looked at the SAIF genome for a SNP in ATM previously associated with metformin response." (PMID 22938532, 2012). "According to previous literature, ATM regulated diabetes mellitus." (PMID 38027164, 2023). "In our study, the effect of metformin in the treatment of diabetes or improvement of relevant glycemic traits was not magnified among the carriers of the C allele at rs11212617 in the ATM gene." (PMID 27386433, 2016). "Therefore, whether the intervention of ATMs or ATMs-sEVs can reduce weight or treat diabetes warrants further research, and the study of the key miRNA/miRNAs within lean ATM-Exos (LATMs-sEVs) improving insulin sensitivity is worthy of future investigation." (PMID 35832790, 2022). "The C/C cells showed differential binding affinity compared to C/T cells in some previously identified TCF7L2 target genes that are involved in diabetes, such as ACSL5, ATM, AKT2, LEF1, and PDK4." (PMID 32651957, 2020). "Besides the effects of ATM-sEVs on insulin function, studies have shown that bone marrow-derived M-sEVs (BMM-sEVs) also play a role in the development of diabetes." (PMID 35832790, 2022).